ENPP2 (ectonucleotide pyrophosphatase/phosphodiesterase 2)
Diseases named in the same sentence as ENPP2 in open-access papers (continued):
Sharing a sentence is not in itself a finding about the gene and the disease.
Lewy body dementia (1 paper, 2020). A progressive form of dementia characterized by the presence of protein deposits called Lewy bodies in the midbrain and cerebral cortex, and loss of cholinergic and dopaminergic neurons. "ENPP2 can be used to specifically discriminate AD from Lewy body dementia, making it a candidate AD biomarker." (PMID 33250918, 2020).
liver disease (1 paper, 2021). "Increased ENPP2 expression is detected in chronic liver disease patients of different etiologies, including HBV-associated liver disease." (PMID 34805271, 2021).
liver fibrosis (1 paper, 2019). "Inhibition of LPA-mediated Heps-HSC crosstalk via genetic deletion of Enpp2 in Heps halted disease progression in that model; in particular, circulatory and hepatic LPA along with liver fibrosis, infiltration of CD68+ macrophages, Gr-1+ monocytes and liver lipid deposition were decreased." (PMID 31652837, 2019).
mastitis (1 paper, 2023). Inflammation of breast tissue during lactation or postpartum due to an obstructed duct or infection. "In the MGI database, we found one gene disruption (Mfge8) and five transgenic mouse models for Lao1, Enpp2, Lpar1, Lpar2, and Lpar3 that resulted in abnormal mammary gland physiology and were also associated with mastitis." (PMID 36759924, 2023).
metastatic tumors (1 paper, 2020). "ATX levels correlate with tumor invasiveness and the ATX gene (ENPP2) is one of the 40–50 most up-regulated genes in metastatic tumors." (PMID 32824846, 2020).
migraine (1 paper, 2025). "Six proteins were significantly upregulated in migraine with a >1.5 fold change compared to controls and Padj < 0.05 (FAM3C, GOLM1, PSA7, ENPP2, DSG2, TFRC); 3 proteins were significantly downregulated (FGL1, CAH2, AMYP)." (PMID 40852402, 2025).
osteoporosis (1 paper, 2025). A condition of reduced bone mass, with decreased cortical thickness and a decrease in the number and size of the trabeculae of cancellous bone (but normal chemical composition), resulting in increased fracture incidence. "Further pQTL-based MR analysis also identified ECM1 and ENPP2 as risk-promoting factors, highlighting the contribution of extracellular matrix organization and lipid metabolism to osteoporosis pathophysiology." (PMID 41029778, 2025).
pregnancy-induced hypertension (1 paper, 2013). "Additionally, decreased levels of serum ENPP2 is associated with pregnancy-induced hypertension, which itself is associated with decreased infant birth weight." (PMID 23866971, 2013).
psoriasis (1 paper, 2023). An autoimmune condition characterized by red, well-delineated plaques with silvery scales that are usually on the extensor surfaces and scalp. "Interestingly, a sixfold increase in the expression of ENPP2 was measured in the PS- samples, compared with HS-, thus showing that Lyso-PLD could be involved in altered NAE signaling in psoriasis." (PMID 37495686, 2023).
renal cell carcinoma (1 paper, 2022). "ENPP2 (Autotaxin) interacts with EC permeability, and ENPP2 expression is associated with acquired resistance against the anti-angiogenic agent sunitinib in renal cell cancer." (PMID 35717322, 2022).
rheumatoid arthritis (1 paper, 2025). A chronic, systemic autoimmune disorder characterized by inflammation in the synovial membranes and articular surfaces. "In addition, expression levels of Mpeg1, Enpp2, Tlr2, CD14, and Lyz2 were examined in the synovial tissues of patients with rheumatoid arthritis (RA) and persistent inflammatory, recurrent, and relapsing arthritis (PIRRA)." (PMID 40787440, 2025).
schizophrenia (1 paper, 2013). A major psychotic disorder characterized by abnormalities in the perception or expression of reality. "Kl was identified as rare risk candidate for schizophrenia together with genes such as insulin-like growth factor binding protein 2 or ectonucleotide pyrophosphatase/phosphodiesterase 2, both upregulated in a rat model for schizophrenia." (PMID 23536833, 2013).
squamous cell carcinoma (1 paper, 2021). A carcinoma arising from squamous epithelial cells. "In order to further verify our findings, we conducted expression, methylation and survival analysis of ENPP2 in PC (all adenocarcinoma cases), LC (adenocarcinoma and squamous cell carcinoma cases) and HCC using the UALCAN database." (PMID 34769391, 2021).
tumor (56 papers, 2009 to 2025). "More specifically, the activation of NF-kB in tumor cells enhances the expression of several genes (including Ccl7, Cxcl1, Ccl5, Slc39a10, Lcn2, Zc3h12a, and Enpp2) that are implicated in tumor migration, angiogenesis, and formation of pre-metastatic niches." (PMID 33567747, 2021). "This is in line with previous studies in LC and BC showing that ENPP2 is hypermethylated in tumor tissues in relation to normal, causing down regulation in gene expression." (PMID 34769391, 2021). "ENPP2 encodes a phospholipase which stimulates tumor cell motility and catalyzes the production of lysophosphatidic acid, which stimulates cell proliferation." (PMID 22142333, 2011). "This association lies in the region between two genes, NOV and ENPP2, which have been shown to play a role in tumor development and motility." (PMID 22142333, 2011). "ENPP2 encodes the autotaxin enzyme which promotes tumor cell migration and metastasis." (PMID 39123378, 2024). "Other features, like tumor mutational burden and tumor stage, did correlate with ENPP2." (PMID 37655662, 2023). "Therefore, it has been confirmed that ENPP2 may play a role in modulating tumor associated immune infiltration in EC." (PMID 39717045, 2024). "Surprisingly, we also found high expression levels of lipid metabolism genes in the B16F10 tumor cell subpopulation, including Gsta4, Gsta2, Gstp1, and Enpp2." (PMID 38755254, 2024). "Many studies have shown that overexpression of ENPP2 inhibits the ability of ferroptosis to prevent the development of hypoxia/reoxygenation (H/R) injury (Fang, Shen & Liao, 2023) and can enhance tumor cell spreading, migration, and metastasis through LPAR1." (PMID 39717045, 2024). "A previous study reported that ENPP2 expression is upregulated in tumor cells following β4 integrins binding to ECM molecules that, in turn, promote cancer cell invasion." (PMID 39201614, 2024). "Enpp2 promotes tumor cell dispersal, migration, and metastasis through LPAR1 and T cell motility through LPAR2." (PMID 37052764, 2023). "On the other hand, ENPP2 was 2.3-fold up-regulated within tumour-adjacent tissue, and FGF2 was 2.4-fold up-regulated in postmenopausal women compared to premenopausal women." (PMID 37509322, 2023). "ENPP2 was 2.4-fold down-regulated in tumour tissue, and LYVE1 was 2.8-fold down-regulated in high-grade cancer compared to low-grade cancer." (PMID 37509322, 2023). "We also constructed a prognostic risk model using the four LMRGs signatures, including ENPP2, MGLL, PLCD1, and SLC44A3, and we found that most of them were correlated with tumor progression." (PMID 37033945, 2023). "The involvement of ENPP2 methylation in tumor progression and prognosis was also addressed by analyzing methylomes from cell lines presenting a more or less aggressively invasive phenotype, revealing several DMCs." (PMID 34769391, 2021). "In order to assess any correlation of ENPP2 methylation to tumor prognosis, clinical characteristics analysis was performed and showed that increased methylation of some CGs was correlated with poor tumor parameters." (PMID 34769391, 2021). "As a result, consistent with their expression changes in tumor samples compared with adjacent samples, ENPP2 and ETS1 showed decreased expression levels in MDA-MB-231, a highly aggressive cell line, compared with MCF-7, a weakly aggressive cell line." (PMID 32412047, 2020). "Upon Hep-specific deletion of Enpp2 in a DEN/CCl4 HCC model there is less HCC tumor growth compared to control mice." (PMID 31652837, 2019). "ENPP2 as their closely-related molecule has been widely reported to participate in tumor development." (PMID 30755833, 2019). "Extracellular LPA is predominantly produced by autotaxin (ATX, also referred to as ENPP2 [ectonucleotide pyrophosphatase/phosphodiesterase family member 2]), an ectoenzyme that was originally identified as a tumor-cell motility-enhancing factor." (PMID 26830463, 2016).
tumor (continued). "TAMs seem to play an essential role in this context, since they express PLA2G7 and ENPP2 at higher levels than tumor cells." (PMID 27215396, 2016). "Consistently, after inhibiting miR-101, SH-SY5Y control cells showed down-regulation of the tumor suppressor EDN1 and CD44 genes, and increased expression of the tumor progression ENPP2 gene with respect to LMNA-KD cells transfected with the miR-101 mimic." (PMID 26439802, 2015). "This agrees with previous observations implicating Enpp2 as being one of the most commonly up-regulated genes in cancer cells and being widely involved in tumor progression, invasion and metastasis." (PMID 20959002, 2010). "ENPP2 has previously been proposed as a source of tumor endothelial cells in ccRCC." (PMID 38414015, 2024). "Therefore, ENPP2 can serve as a specific biomarker for tumor-derived endothelial cells and a prognostic indicator." (PMID 38414015, 2024). "Enpp2 codes for a soluble, secreted lysophospholipase D, also known as autotaxin, that can promote tumor progression because it can both promote motility of cancer cells in an autocrine manner as well as inhibit motility of immune cells, acting as a chemorepellent." (PMID 38631901, 2024). "Finally, immune infiltration and the tumor microenvironment (TME) were explored to examine the involvement of ENPP2 in EC progression." (PMID 39717045, 2024). "Furthermore, in vitro investigations were performed to explore the functional role of ENPP2 and its ability to enhance tumor proliferation, migration, and invasion were discovered." (PMID 39717045, 2024). "Bioinformatic analyses revealed five major cell types based on hallmark gene expression: myeloid (Cd11b; 12 clusters), lymphoid (Cd33/Ncr1/B220/Cd19; 5 clusters), tumor (Olig2/Cd276/Col11a1; 1 cluster), endothelial (Enpp2; 1 cluster) and fibroblast (plp1/Ptgds; 1 cluster) cells." (PMID 37333156, 2023). "Bioinformatic analyses revealed five major cell types based on hallmark gene expression: myeloid (Cd11b; 12 clusters), lymphoid (Cd33/Ncr1/B220/Cd19; five clusters), tumor (Olig2/Cd276/Col11a1; one cluster), endothelial (Enpp2; one cluster), and fibroblast (plp1/Ptgds; one cluster) cells." (PMID 37971169, 2023). "Six overall survival associated genes (ENPP2, ULK1, CP, LURAP1L, HIC1, AKR1C1) were selected to build survival model, of which hub gene AKR1C1 was with high expression and low ferroptosis level in NSCLC tumor." (PMID 34702254, 2021). "In addition, compared with immune-competent mice that received control PDAC cells in the pancreas, mice that received Enpp2 ko PDAC cells exhibited compromised tumor growth." (PMID 34200030, 2021). "This molecule has not been widely studied but the closely-related molecule ENPP2 (autotaxin) has been widely implicated in neoplasia and is the focus of considerable efforts to develop small molecule inhibitors." (PMID 22311740, 2012). "The extracellular secretion of APE1 and ENPP2 induced by oxidative stress indicates a potential role for these proteins outside the cell, where they may function as paracrine signaling molecules that enhance the invasive tumor microenvironment." (PMID 41009025, 2025). "Additionally, ENPP2 may regulate the tumor immune microenvironment through its interaction with immune cells in EC." (PMID 39717045, 2024). "In addition, it has been shown that the tumor suppressor microRNA-101-3p could bind to the 3′-UTR of ENPP2 mRNA and inhibit its translation, leading to the reduction of migration, invasion and proliferation." (PMID 36358855, 2022). "Interestingly, in the tumor samples, increased methylation of the majority of the ENPP2 CGs (cg00320790, cg01243251, cg02156680, cg02709432, cg07236691, cg09444531, cg14409958, cg20048037, cg20162626, cg23725583) (all p < 0.05) was noticed in women in relation to men." (PMID 34769391, 2021). "In conclusion, we identified a novel anti-tumor subcluster of M2-like TAMs with high expression of SLC12A5 and ENPP2 as bM2-like TAMs." (PMID 39507421, 2024).
tumor (continued). "Other genes were modulated in a different way in all three SCCs (NMNAT1, NMNAT2, NADSYN1, SIRT3, and CD38) or in two tumor types (NNMT, NMNAT3, ENPP2, PNP, and SIRT1)." (PMID 38254798, 2024). "In a group of patients with stages IB–IV EC (n = 11), TIMP2, CSF3, ENPP2, and SERPINF1 were significantly down-regulated in tumour tissue, by 4.9-fold, 9.6-fold, 10.2-fold, and 9.2-fold, respectively." (PMID 37509322, 2023). "In fact, it is now established that the direct production of ENPP2 mRNA by cancer cells is significantly low in many cancer types and the majority of ATX is produced from the tumor microenvironment." (PMID 36358855, 2022). "As an example, the tumor endothelium can be classified into four distinct subclusters also enabling the annotation of INSR as PCa tip cell marker and Fibulin5 and ENPP2 as PCa artery specific markers." (PMID 35717322, 2022). "In TAMs compared to non-tumor macrophages, MMP12, a protease involved in macrophage migration and the regulators of lymphocyte homing and inflammation ENPP2, MERTK and F13A1 were upregulated." (PMID 33918618, 2021). "Among these, we found some tumor suppressor genes (e.g. H19, ACTN4) that were down-regulated and some genes related to tumor progression and metastasis formation (e.g. ENPP2, GRIA3, TPM3) that were up-regulated." (PMID 23049808, 2012). "We extended this finding by identifying ENPP2 as a marker for tumor artery and capillary-derived endothelial cells, rather than tumor venous endothelial cells." (PMID 38414015, 2024). "However, NMRGs with significant AUC values (ENPP1, ENPP2, NAMPT, SIRT1, PARP1, NMNAT1, and PNP) were differentially expressed among tumor grades." (PMID 38254798, 2024). "CpG islands located at RIIAD1, ENPP2, ESPN, and ETS1, were hyper-methylated in BC tumor." (PMID 38082340, 2023). "In premenopausal patients (n = 11), six genes were statistically significantly down-regulated in tumour tissue compared to tumour-adjacent tissue: TIMP3 (13.1-fold), ENPP2 (11.4-fold), FGF2 (7.6-fold), CXCL12 (7.5-fold), TIMP2 (5.2-fold), and PDGFRB (4.9-fold change)." (PMID 37509322, 2023). "A limitation of our study is the small number of patients enrolled in the experimental part not allowing significant correlations between ENPP2 methylation levels and clinicopathological features such as grade and tumor size to emerge." (PMID 35409077, 2022). "Although elevated ENPP2 levels have been observed in cancer patients, most of the produced ENPP2 is proposed to originate from the tumor surrounding environment rather than directly from the cancer cells themselves." (PMID 36358855, 2022). "Herein, we want to verify whether ENPP2 is a factor that connects HBV infection and tumor progression in HBV-related HCC." (PMID 34805271, 2021). "Besides, expressions of ENPP2 and ETS1 were significantly decreased in BRCA tumor samples, and ESPN and RIIAD1 were significantly elevated in BRCA tumor samples compared with adjacent normal samples." (PMID 32412047, 2020). "Finally, no other correlation emerged between ENPP2 methylation and grade, nodal status, tumor size, or age." (PMID 35409077, 2022).
cancer (41 papers, 2007 to 2025). A tumor composed of atypical neoplastic, often pleomorphic cells that invade other tissues. "Significantly, a correlation was observed between the expression of ENPP2 and several immune cell types, including endothelial cells, regulatory T cells, cancer-associated fibroblasts, hematopoietic stem cell_XCELLs, and activated mast cells." (PMID 39717045, 2024). "Apoptosis increased in the Enpp2-knockdown tumors using either loss-of-function approach, indicating a role for cancer cell-derived ATX in PDAC progression, which suppresses tumor cell death." (PMID 38195933, 2024). "We investigated the associations between genetic polymorphisms of the ENPP2 gene and two types of nociceptive pain: postoperative pain and cancer pain." (PMID 37108150, 2023). "For example, ENPP2, which encodes autotaxin, is overexpressed in chronic inflammatory diseases and cancer and synthesizes lysophosphatidic acid." (PMID 37033945, 2023). "ENPP2 is essential for normal development, is implicated in various physiological processes, and is also associated with pathological conditions including cancer." (PMID 34805271, 2021). "Autotaxin (ATX) encoded by Ectonucleotide Pyrophosphatase/Phosphodiesterase 2 (ENPP2) is a key enzyme in Lysophosphatidic Acid (LPA) synthesis implicated in cancer." (PMID 34769391, 2021). "Intriguingly, the ATX encoding gene, ENPP2, resides in the human chromosomal region 8q24, a region that contains potential susceptibility loci for different types of cancer." (PMID 31652837, 2019). "The gene encoding ATX (ENPP2) is among the 40 most upregulated genes in highly metastatic cancers with lysoPLD activity correlating with poor prognosis." (PMID 24278115, 2013). "ENPP2, which encodes the enzyme autotaxin, was found to be over-expressed in various cancers." (PMID 32373530, 2020). "In addition, Enpp2 was identified as one of 90 genes associated with drug resistance in cancer." (PMID 37795611, 2023). "The relevant ENPP2 SNPs and their respective models demonstrated significant associations with the numeric rating scale (NRS) of cancer pain intensity, although the total daily opioid doses were comparable." (PMID 37108150, 2023). "This type of cancer often overexpresses autotaxin, which is also known as ectonucleotide pyrophosphatase/phosphodiesterase 2, and produces lysophosphatidic acid (LPA) from lysophosphatidylcholine extracellularly." (PMID 37158894, 2023). "Our bioinformatic analysis also showed that ENPP2 methylation was increased in metastasis in relation to primary cancers." (PMID 36358855, 2022). "HuR acts through stabilizing the ENPP2 mRNA and leads to increased ENPP2 expression, while AUF1 promotes ENPP2 decay and suppress ENPP2 expression; it was suggested that via these mechanisms they can modulate cancer cell migration." (PMID 36358855, 2022). "Our bioinformatic analysis also showed that ENPP2 methylation is increased in metastasis in relation to primary cancers." (PMID 35409077, 2022). "Taken together, these results suggest that several mechanisms are implicated in mRNA/protein ENPP2 expression and LPA signaling in tumors during cancer pathogenesis, building a complex and possibly tissue-specific process." (PMID 36358855, 2022). "The most enriched KEGG pathways were related to the ribosome (RPS5, RPS9), focal adhesion signaling pathways (FGL, SPP1), synaptic vesicle cycle (CLTC), and ether lipid metabolism (ENPP2), which were related to the invasion and metastasis of cancer." (PMID 36276156, 2022). "ENPP2 expression can be altered by several inflammatory cytokines and growth factors, frequently increased in cancer." (PMID 36358855, 2022).